SNORD58A (small nucleolar RNA, C/D box 58A)
Synonyms: U58a; RNU58A
Gene: Small nucleolar RNA gene on chromosome 18 (49,491,283 to 49,491,347, reverse strand). Ensembl gene ENSG00000206602.
Gene Ontology:
Biological process: RNA processing
Cellular component: nucleolus
Homologues: Orthologues: macaque SNORD58 (97% identical), rat LOC120098352 (95% identical), guinea pig SNORD58 (94% identical), mouse Gm23301 (91% identical), pig SNORD58 (91% identical), rabbit SNORD58A (85% identical), dog SNORD58 (80% identical), tropical clawed frog SNORD58 (78% identical). Paralogues in human: SNORD58B (80% identical), SNORD58C (78% identical), SNORD58 (72% identical).